RN7SKP120 (RN7SK pseudogene 120)
Gene: Miscellaneous RNA gene on chromosome 9 (25,088,811 to 25,089,151, reverse strand). Ensembl gene ENSG00000222693.
Homologues: Orthologues: chimpanzee 7SK (98% identical). Paralogues in human: RN7SKP146 (68% identical), RN7SKP245 (68% identical), 7SK (67% identical), RN7SKP133 (67% identical), RN7SKP184 (67% identical), RN7SKP79 (67% identical), RN7SKP9 (67% identical), RN7SKP160 (66% identical), RN7SKP8 (66% identical), RN7SKP86 (66% identical), RN7SKP180 (66% identical), RN7SKP217 (66% identical), and 283 more.